HMGB2 (high mobility group box 2)
Diseases named in the same sentence as HMGB2 in open-access papers (continued):
Sharing a sentence is not in itself a finding about the gene and the disease.
HMGB2 also shares sentences with these, for which no sentence is quoted: cervical squamous cell carcinoma (3 papers); acute myeloid leukemia (2); Cirrhosis (2); colon cancer (2); colorectal (2); endocervical adenocarcinoma (2); heart failure (2); lung squamous cell carcinoma (2); malaria (2); Neurological Disorder (2); osteosarcoma (2); adrenocortical carcinoma (1); chronic lymphocytic leukemia (1); diabetic kidney disease (1); dilated cardiomyopathy (1); gastrointestinal stromal tumor (1); gynecological cancer (1); head and neck squamous cell carcinoma (1); hyperlipidemia (1); Hypertension (1); Hypoglycemia (1); infarction (1); inflammatory bowel disease (1); invasive breast carcinoma (1); leiomyosarcoma (1); malignant mesothelioma (1); multiple myeloma (1); neurodegenerative disease (1); non-small cell lung carcinoma (1); Obesity (1).
A further 13 diseases each share a sentence with HMGB2 in 1 paper.